PDGFRB (platelet derived growth factor receptor beta)
Diseases named in the same sentence as PDGFRB in open-access papers (continued):
Sharing a sentence is not in itself a finding about the gene and the disease.
chlamydial infection (2 papers, 2015 to 2021). "We did not detect PDGFRβ or reproducibly detect ITGβ1 by proximity labeling, both of which have been shown to promote C. trachomatis attachment and entry, yet detection of amino acid transport proteins that are relevant to chlamydial infection was apparent." (PMID 33468693, 2021).
choroidal neovascularization (2 papers, 2012 to 2021). An eye disorder described by the growth of new blood vessels that originate from the choroid through a break in the Bruch membrane into the sub–retinal pigment epithelium (sub-RPE) or subretinal space. "We also show that specific ablation of PDGFRβ-overexpressing pericytes using an ADC potently inhibits pathologic ocular neovascularization in mouse models of oxygen-induced retinopathy and laser-induced choroidal neovascularization, while not provoking generalized retinal toxicity." (PMID 35602228, 2021).
chronic asthma (2 papers, 2015 to 2020). An asthma that is characterized by the development of persistent airway inflammation and recurrent attacks of breathlessness and wheezing, which vary in severity and frequency. "However, it is not known whether PDGF-BB signaling via PDGFRβ, which is critical for the recruitment of pericytes to blood vessels, plays a role in airway remodeling in chronic asthma." (PMID 25637607, 2015).
dyslipidemia (2 papers, 2023 to 2024). "Besides, PDGFRB variants rs3828610 and rs9324641 had significant relationship with a higher risk of CAD in the subgroup with dyslipidemia (p = 0.009; p = 0.029)." (PMID 39569832, 2024).
esophageal squamous cell carcinoma (2 papers, 2017 to 2018). Esophageal squamous cell carcinoma (ESCC) is a type of esophageal carcinoma (EC) that can affect any part of the esophagus, but is usually located in the upper or middle third. "Similarly, PDGFRB was also overexpressed (1.5~15.4 folds) in esophageal squamous cell carcinoma and esophageal adenocarcinoma patients." (PMID 28147311, 2017).
essential thrombocythemia (2 papers, 2020 to 2021). A chronic myeloproliferative neoplasm that involves primarily the megakaryocytic lineage. "The expression level of PDGFB and PDGFRB in the bone marrow of essential thrombocythemia patients were significantly higher than in normal controls." (PMID 32235327, 2020). "No rearrangement of PDGFRA, PDGFRB, FGFR1, or PCM1-JAK2; the Philadelphia chromosome; or BCR-ABL1 gene fusion should be detected as any diagnostic criteria for polycythemia vera (PV), essential thrombocythemia (ET), and primary myelofibrosis (PMF)." (PMID 34684141, 2021).
glaucoma (2 papers, 2020 to 2024). Increased pressure in the eyeball due to obstruction of the outflow of aqueous humor. "Bioinformatic analysis of POAG‐related autoantigens showed a strong association with the PDGFRB pathway and also increased levels of PNMA2, TARS, and C1QBP autoantibodies in the serum of POAG patients as potential glaucoma biomarkers." (PMID 32140226, 2020).
glomerulonephritis (2 papers, 2013 to 2025). A renal disorder characterized by damage in the glomeruli. "Furthermore, in the glomerulonephritis patients and in rodent models of mesangioproliferative glomerulonephritis both B-chain and PDGFRβ are increased." (PMID 39761275, 2025).
Hepatic steatosis (2 papers, 2024 to 2025). Steatosis is a term used to denote lipid accumulation within hepatocytes. "Of note, the liver lipid accumulation was remarkably reduced by ~ 25% in obese Hif1a-bKO mice after 8 weeks HFD feeding, highlighting the protective effects on the development of fatty liver disease via HIF1α suppression in PDGFRβ + cells." (PMID 38509584, 2024). "This study poses limitations represented by that the potential involvement of Epas1 inactivation within liver PDGFRβ + cells cannot be ruled out as a factor in the control of hepatic steatosis, a caveat to the mouse models." (PMID 38509584, 2024).
hyperlipidemia (2 papers, 2015 to 2021). "In the setting of hyperlipidemia, PDGFRβ signaling promotes new plaque formation in the subendothelium of the thoracic aorta and is closely associated with inflammation of the adventitia and media." (PMID 34094640, 2021).
infantile hemangiomas (2 papers, 2021 to 2025). "Recent studies suggest a central role of somatic PDGFRB mutations in the development of infantile hemangiomas and (intracerebral) aneurysms." (PMID 40632343, 2025). "Although PDGFRβ is a mural cell marker in the vasculature, it is also expressed in circulating endothelial progenitors, hemangioblasts, and the immature proliferative endothelium of infantile hemangiomas." (PMID 34043714, 2021).
intracranial aneurysms (2 papers, 2022 to 2024). "Although PDGFRB somatic variants have been identified in fusiform intracranial aneurysms, the molecular and cellular mechanisms driving fusiform intracranial aneurysms due to PDGFRB somatic variants remain poorly understood." (PMID 38741091, 2024). "Among them, the NF-κb pathway has been shown to be associated with the activation of PDGFRB mutation in intracranial aneurysms." (PMID 38741091, 2024). "Whole-exome sequencing was performed on seven intracranial aneurysms (six fusiform and one saccular) and PDGFRB somatic mutations were detected in four fusiform aneurysms." (PMID 38741091, 2024). "Whole-exome sequencing revealed the presence of PDGFRB gene mutations in fusiform intracranial aneurysms." (PMID 38741091, 2024). "Specific biomarkers for intracranial aneurysm provide a potential therapeutic avenue for intracranial aneurysms, such as platelet-derived growth factor receptor β gene (PDGFRB)." (PMID 36505409, 2022).
Kaposi's sarcoma (2 papers, 2022 to 2025). A malignant neoplasm characterized by a vascular proliferation which usually contains blunt endothelial cells. "In Kaposi’s sarcoma (KS) specimens, LANA-positive cells exhibited low CD31 with high expression of mesenchymal markers (SMA, PDGFRβ, CD146), consistent with EndMT in infected cells." (PMID 41154806, 2025).
lung disease (2 papers, 2021 to 2025). "This study demonstrates the specific uptake of [18F]TZ-Z09591 in PDGFRβ-expressing tissues, particularly in pulmonary lesions, across two lung disease models: BLM-induced lung injuries in rats and ARDS in pigs." (PMID 40664934, 2025). "Before assessing [18F]TZ-Z09591 in lung disease models, we validated its in vivo specificity in mice xenografted with PDGFRβ-expressing U-87 cells." (PMID 40664934, 2025).
muscular dystrophy (2 papers, 2016 to 2022). Muscular dystrophy (MD) refers to a group of more than 30 genetic diseases characterized by progressive weakness and degeneration of the skeletal muscles that control movement. "Muscle-resident PDGFRβ+ cells, which include pericytes and PW1+ interstitial cells (PICs), play a dual role in muscular dystrophy." (PMID 27138650, 2016).
myofibroma (2 papers, 2024 to 2025). A benign, localized, nodular and well-circumscribed neoplasm usually seen as a congenital neoplasm or in the first year of life. "A recent large-scale study, which included 69 patients with myofibroma, did not identify PDGFRB mutations in tumors in patients older than 18 years." (PMID 39583463, 2024).
myopericytoma (2 papers, 2024 to 2025). A usually slow growing, subcutaneous nodular neoplasm arising from myopericytes. "Among these genetic abnormalities, PDGFRB somatic mutations are associated with sporadic myopericytomas." (PMID 38978924, 2024).
myxoid liposarcoma (2 papers, 2016 to 2019). A liposarcoma characterized by the presence of round non-lipogenic primitive mesenchymal cells and small signet ring lipoblasts within a myxoid stoma with a branching vascular pattern. "Moreover imatinib, which targets the same receptors as axitinib, except the VEGFRs, reduced the phosphorylation of c-Kit and PDGFRβ but did not inhibit myxoid liposarcoma cell proliferation/survival at a biologically relevant dose." (PMID 27822137, 2016).
overgrowth syndrome (2 papers, 2017 to 2025). A group of syndromes caused by genetic birth defects that may lead to the development of malignancies. "Interestingly, mutations in PDGFRB also cause autosomal-dominant infantile myofibromatosis, Penttinen syndrome, and a novel overgrowth syndrome characterized by somatic overgrowth, distinctive facial features, hyper-elastic and fragile skin, white matter lesions, and neurologic deterioration." (PMID 28935882, 2017).
PEComas (2 papers, 2017 to 2025). "PEComas with TSC1/2 mutations or TFE3 rearrangements respond to mTORC1 inhibition, while IMTs harboring ALK, RET, PDGFRB, or NTRK rearrangements demonstrate marked responses to ALK or TRK inhibitors." (PMID 41463261, 2025).
skin carcinoma (2 papers, 2019 to 2022). "Furthermore, an elevated expression of platelet-derived growth factor receptor ß (PDGFRB) was observed across all three tumors, which has been reported to promote distant metastasis in cancer stem cells of advanced skin carcinoma." (PMID 35055192, 2022).
skin tumors (2 papers, 2022). "We conclude that α11β1 operates in a subset of skin tumor CAFs, likely in co-operation with PDGFRβ signaling, thereby regulating ECM synthesis and collagen assembly to encourage cSCC growth and progression." (PMID 36003785, 2022). "Nevertheless, our findings on reduced PDGFRβ expression in the absence of α11, not only in Itga11-/- skin tumor stroma but also in chronically inflamed dermis, suggest the need for further studies on integrated α11β1 and PDGFRβ signaling." (PMID 36003785, 2022). "Our attempts to establish CAF lines from Itga11-/- skin tumors using either the explant method or anti-PDGFRα antibody-based FACS were not successful, and thus, the functions and molecular mechanisms involving α11, PDGFRβ and TNC could not be studied further under in vitro conditions." (PMID 36003785, 2022).
T-lymphoblastic lymphoma (2 papers, 2012 to 2025). The most frequent type of lymphoblastic lymphoma. "Although such genetic mutations are prone to multi-lineage differentiation, the present case is in fact the first report of concurrent AML and T lymphoblastic lymphoma involving PDGFRB mutations." (PMID 22356850, 2012). "In humans, concurrent myeloid neoplasms and T lymphoblastic lymphoma have been reported with FIP1L1-PDGFRA fusion genes but not with any PDGFRB rearranged genes." (PMID 22356850, 2012).
temporal lobe epilepsy (2 papers, 2019 to 2024). A localization-related (focal) form of epilepsy characterized by recurrent seizures that arise from foci within the temporal lobe, most commonly from its mesial aspect. "An increase in ramified PDGFRβ+ parenchymal cells was observed in human temporal lobe epilepsy (TLE) that co‐localized with NG2 but not Iba1 41 and their redistribution showing the following experimental status suggests that they are reactive populations." (PMID 30636077, 2019).
thyroid (2 papers, 2016 to 2025). "Integration with conventional DEG signatures revealed a functionally cohesive module, with C1QA/B/C, FLT1, TEK, PDGFRB, SPP1, and HLA-DPB1 emerging as central regulators of thyroid irAEs." (PMID 41221294, 2025).
tongue squamous cell carcinoma (2 papers, 2024 to 2025). A squamous cell carcinoma that arises from the tongue. "Additionally, flow cytometric analysis of murine tongue squamous cell carcinoma showed that the positive CD74+PDGFRB+ apCAFs was 1.37% in the murine tongue squamous cell carcinoma while we could not find any positive CD74+PDGFRB+ apCAFs in the normal control tissue." (PMID 39891284, 2025).
ulcer (2 papers, 2013 to 2016). "An increased presence of the PDGFRβ-positive cells was also observed in ulcer (10/10) in the granulation tissue, which forms during the healing process." (PMID 27128408, 2016).
urothelial carcinoma (2 papers, 2022 to 2025). A malignant neoplasm derived from the transitional epithelium of the urinary tract (urinary bladder, ureter, urethra, or renal pelvis). "Interestingly, targeted sequencing identified four mutations shared by all of the tissue samples, including the urothelial carcinoma: BRCA1 p.Val340GlyfsTer6, DICER1 p.Arg490His, IRS2 p.Arg744Cys, and PDGFRB p.Arg853Trp." (PMID 35260767, 2022).
uveal melanoma (2 papers, 2020 to 2025). A melanoma derived from melanocytes of the uveal tract. "Imatinib, by inhibiting PDGFRβ activation and, consequently, CAF transition, could be able to counteract uveal melanoma invasiveness." (PMID 32756477, 2020).
vasculitis (2 papers, 2024 to 2025). "Vascular upregulation of PDGFRB on pericapillary pericytes with enlarged capillary lumina was observed in all cases (10/10; 100%), and this feature was pronounced close to the vasculitis areas more prominently than at a distance." (PMID 41441888, 2025). "In this KD‐like vasculitis mouse model, PDGFRβ overexpression was also observed in the thickened medial layer and vascular endothelium." (PMID 39424429, 2024).
alcohol abuse (1 paper, 2024). The use of alcoholic beverages to excess, either on individual occasions ("binge drinking") or as a regular practice. "Expression of FAP, α-SMA, PDGFRb or periostin was independent from nicotine or alcohol abuse, UICC stage, sex or HPV status." (PMID 38328551, 2024).
Anxiety (1 paper, 2021). Intense feelings of nervousness, tension, or panic often arise in response to interpersonal stresses. "Knowledge of a family history of IM or familial PDGFRB variants may cause substantial anxiety." (PMID 32888134, 2021).
arteriovenous malformations (1 paper, 2024). "Extracranial arteriovenous malformations (eAVMs) contain a heterogeneous population of both CD31+ and CD31- vascular endothelial cells (eAVM-ECs), the latter of which line grossly dilated vessels and are surrounded by an expanded perivasculature of PDGFRβ+ mural cells (eAVM-MCs)." (PMID 39768212, 2024).
Ascites (1 paper, 2024). Accumulation of fluid in the peritoneal cavity (between the layers of the peritoneum that lines the abdomen). "If only PDGFR had a role in the development of dasatinib-related PE, PDGFRβ inhibition would have caused increased capillary permeability, leading to ascites due to the changes in interstitial pressure." (PMID 38558869, 2024).
basal cell carcinoma (1 paper, 2022). A carcinoma involving the basal cells. "Using NGS technology, in basal cell carcinoma were identified 65 differentially expressed genes coding for ECM components and CAF markers such as fibroblast activation protein alpha (FAP-alpha) and platelet-derived growth factor receptor beta (PDGFR-beta)." (PMID 35558554, 2022).
benign meningioma (1 paper, 2014). A grade I, slowly growing meningioma. "Additionally, epidermal growth factor receptors (EGFR) tend to be overexpressed in benign meningiomas, and the platelet-derived growth factor receptor beta (PDGFRB) gene is also upregulated and overexpressed in benign meningioma." (PMID 25485306, 2014).
bone metastasis (1 paper, 2015). Transfer of a neoplasm from its primary site to bones. "Stromal podoplanin, S100A4, and PDGFRα expression was elevated in bone metastasis, while tumoral podoplanin and stromal PDGFRβ expression was elevated in lung metastasis." (PMID 26163388, 2015).
Burkitt lymphoma (1 paper, 2019). A rare form of malignant mature B-cell non-Hodgkin lymphoma. "Our results revealing highly phosphorylated EGFR, PDGFRβ, ROR2, ERK1/2, or Hsp27 in all samples are also in accordance with previously published findings on Burkitt lymphoma." (PMID 32117783, 2019).
carotid body paraganglioma (1 paper, 2021). A benign or malignant extra-adrenal parasympathetic paraganglioma arising from paraganglia adjacent to or in the bifurcation of the common carotid artery. "It has been shown that carotid body paragangliomas in people, which are biologically similar to chemodectomas in dogs often overexpress VEGFR1, VEGFR2, PDGFRα, and PDGFRβ, making them potential targets for treatment with tyrosine kinase receptor inhibitors such as sunitinib." (PMID 33614771, 2021).
cataract (1 paper, 2024). Partial or complete opacity of the crystalline lens of one or both eyes that decreases visual acuity and eventually results in blindness. "Based on this, it was speculated that PDGFRB and CDKN1A were promoting genes, and PTEN, CANX, COL4A2, EIF2S1, and NPM1 were suppressing genes in cataract pathogenesis." (PMID 38662949, 2024).
cerebral aneurysms (1 paper, 2021). "As PDGFRB germline variants associated with IM were recently also linked to the development of cerebral aneurysms, a single MRI examination of the brain at the age of 15–18 years to screen for cerebral aneurysms can be considered." (PMID 32888134, 2021). "Additional features associated with PDGFRB germline variants include cerebral aneurysms." (PMID 32888134, 2021).
cerebrovascular disease (1 paper, 2025). "Future studies should focus on elucidating the molecular crosstalk between PDGFRβ and ALK1, and on developing targeted therapies that restore balance to this signaling axis in cerebrovascular disease." (PMID 41001557, 2025).
cholestasis (1 paper, 2024). Impairment of the bile flow caused by obstruction within the liver, or outside the liver in the bile duct system. "PDGFRβ was identified as a hub protein, suggesting that YCZFD exerts a protective effect against cholestasis by alleviating fibrosis through the regulation of PDGFRβ." (PMID 38469403, 2024).
chronic leukemia (1 paper, 2013). A slowly progressing leukemia characterized by a clonal (malignant) proliferation of maturing and mature myeloid cells or mature lymphocytes. "The genetic abnormality in chronic leukemias with hypereosinophilia appears to be based entirely on the PDGFRB mutation." (PMID 23936692, 2013).
colorectal adenocarcinoma (1 paper, 2012). The most common type of colorectal carcinoma. "The present study evaluated the incidence of VEGFR2, PDGFRα and PDGFRβ TK domain genetic variants in different CRC cell lines (T84, LOVO, LS174T, HT29, LS180, SW48, SW480, COLO205) and in tumor samples of 92 patients diagnosed of colorectal adenocarcinoma." (PMID 23146028, 2012).
congenital heart disease (1 paper, 2016). A heart disease that is present at birth. "Previous studies have shown that lack of PDGFRβ signaling is related to a complex heart phenotype with defects in ventricular septum formation and development of atrioventricular valves, and might be of importance in congenital heart disease." (PMID 27032083, 2016).
coronary artery disease (1 paper, 2024). "We aimed to investigate the association of genetic variations and mRNA expressions of PDGF/PDGFRB pathway genes with coronary artery disease (CAD)." (PMID 39569832, 2024).
Crohn disease (1 paper, 2025). A gastrointestinal disorder characterized by chronic inflammation involving all layers of the intestinal wall, noncaseating granulomas affecting the intestinal wall and regional lymph nodes, and transmural fibrosis. "Ileal tissues from CDS patients had higher PDGFRb phosphorylation than those from nonstricturing Crohn’s disease (CDNS) patients, suggesting an enhanced PDGFRβ activity in intestinal strictures." (PMID 40398622, 2025).
dermatitis (1 paper, 2020). An inflammatory process affecting the skin. "We determined the levels of RTKs (VEGFR1, PDGFRB and FGFR2) from dermatitis patients and normal controls using meta-analyses." (PMID 32161331, 2020). "We found PDGFRB and FGFR2 were increased from dermatitis patients compared to normal control." (PMID 32161331, 2020).
diabetic retinopathy (1 paper, 2023). "In this study, intravitreal injection of BIBF1120 blocked the phosphorylation of VEGFR2, FGFR1, PDGFRβ, and MAPK signaling pathway proteins in a streptozotocin (STZ)-induced diabetic retinopathy mouse model." (PMID 37152616, 2023).
dysplasia (1 paper, 2021). A usually neoplastic transformation of the cell, associated with altered architectural tissue patterns. "The proliferative fractions of PDGFRβ cells were higher in FCD3a than FCD2 but at similar levels to TLE/HS without dysplasia." (PMID 33370704, 2021).